KL (klotho)
Diseases named in the same sentence as KL in open-access papers (continued):
Sharing a sentence is not in itself a finding about the gene and the disease.
Hypertension (continued). "Klotho, possibly an age-regulating protein, is considered an important factor contributing to the lifespan and pathophysiology of hypertension and coronary artery disease (CAD)." (PMID 30547758, 2018). "The Klotho level decreases with age (Xiao, Zhang, Zheng & Gu, 2004), while the prevalence of arterial stiffness and hypertension increases with age." (PMID 29659128, 2018). "Our data suggest that compound H increased DNA demethylase activity in kidneys and increased renal Klotho expression and circulating klotho levels which largely explain the beneficial effect of compound H on arterial stiffening and hypertension." (PMID 29659128, 2018). "Compound H activates demethylases and attenuates arterial stiffening and hypertension in aged mice likely via increasing the Klotho levels." (PMID 29659128, 2018). "It is new and interesting that compound H activates DNA demethylase which induces Klotho expression and release leading to attenuation of arterial stiffening and hypertension in aged mice." (PMID 29659128, 2018). "In the present study, Klotho C1818T gene polymorphism was attributed to the decreased risk of hypertension and CAD combined with hypertension." (PMID 30547758, 2018). "The in vivo study showed that compound H increased circulating levels of Klotho and attenuated arterial stiffening and hypertension in aged mice." (PMID 29659128, 2018). "Various animal models of human hypertension, SHRs, deoxycorticosterone acetate-salt hypertensive rats, and 5/6 nephrectomized rats indicate that sustained circulatory stress inhibits klotho expression." (PMID 27885332, 2016). "Since then, more than 10 SNPs in the human Klotho gene have been identified, among which, the G-395A (rs1207568) SNP in the promoter region of Klotho gene was related to hypertension or high systolic blood pressure 10 in previous studies in previous studies." (PMID 26880028, 2016). "A modest amelioration of proteinuria and renal function were observed when KL was overexpressed genetically in the chronic glomerulonephritis model or via viral delivery in the chronic angiotension ii hypertension model." (PMID 24224012, 2013). "Klotho expression is also downregulated in an animal model of spontaneous hypertension, and the delivery of Klotho has been shown to prevent the progression of hypertension, renal damage, and the proteinuria." (PMID 22121479, 2012). "In the fully adjusted model (Model 2), which accounted for age, sex, smoking, creatinine, klotho, hypertension, and dysglycemia, each log2-unit increase in serum butyraldehyde was associated with a 36.7% reduction in the odds of AAC (adjusted OR = 0.633; 95% CI 0.436–0.930; p = 0.016)." (PMID 41495777, 2026). "s-Klotho has been shown to enhance endothelial function, reduce oxidative stress, and inhibit vascular calcification, mechanisms central to cardiovascular diseases like atherosclerosis and hypertension [693, 1365]." (PMID 40407975, 2025). "Additionally, our findings suggested that Klotho exhibited significant protection against CMDs specifically among current smokers and individuals with hypertension history." (PMID 40369033, 2025). "Clinically, serum Klotho levels are reduced in both hypertension and obesity." (PMID 40869353, 2025). "Recent retrospective studies suggested that Klotho may serve as a promising biomarker for a range of age-related diseases such as heart failure, hypertension, diabetes and cardiovascular mortality." (PMID 41303567, 2025). "Moreover, current knowledge of circulating serum klotho levels as a predictor for hypertension in humans is limited." (PMID 39616409, 2024). "In our study, participants with higher Klotho levels were likely to be female and had hypertension." (PMID 39777219, 2024). "However, our results found that Klotho was independently associated with cardiovascular mortality in patients with CKD and was more pronounced in patients with hypertension." (PMID 38409304, 2024).
Hypertension (continued). "Patients with lower Klotho levels are more likely to be older patients, to be smokers, to have hypertension and CVD, to be less likely to meet suggested physical activity guidelines, and to have higher 25(OH)D levels and lower DBP, eGFR, fasting glucose or HbA1c levels." (PMID 38409304, 2024). "The results showed that the negative association between serum S-Klotho and OA remained stable when stratified by gender, age, race, BMI, hypertension, and DM." (PMID 39556550, 2024). "The interaction with hypertension further complicates Klotho’s role in kidney function." (PMID 39777219, 2024). "Also, recombinant Klotho therapy has been shown to exert protective actions on myocardial ischaemia–reperfusion injury, insulitis in diabetic subjects and hypertension in various models." (PMID 38213484, 2024). "In preclinical studies, klotho was found to be protective against the development of hypertension." (PMID 39616409, 2024). "We found a significant negative correlation between ln(Klotho) and ePWV in postmenopausal women without hypertension, independent of other cardiovascular risk factors." (PMID 39329104, 2024). "First, we have not performed an analysis regarding the potential confounding factors that may affect serum klotho levels and cardiovascular or renal outcomes, including hypertension, atherosclerotic cardiovascular disorders, physical inactivity and smoking." (PMID 39281418, 2024). "Hypertension may affect the relationship between serum Klotho level and ePWV in postmenopausal women." (PMID 39329104, 2024). "Possible explanations include the following: First, previous studies with smaller sample sizes might have overlooked the impact of hypertension on the relationship between Klotho and ePWV." (PMID 39329104, 2024). "Understanding klotho’s role in essential hypertension may lead to the development of novel therapeutic strategies for this disease." (PMID 39616409, 2024). "Higher serum Klotho concentration was associated with lower all-cause mortality, but not cardiovascular mortality in patients with hypertension with or without chronic renal impairment." (PMID 36457804, 2022). "By activating the non-canonical Wnt5a/RhoA pathway, Klotho deficiency increases salt sensitivity in patients with hypertension which leads to increased total peripheral resistance via vasoconstriction, therefore raising BP." (PMID 36457804, 2022). "Early diagnosis of low Klotho concentration (particularly <574 pg/mL) and appropriate intervention in patients with hypertension may be a possible target for preventing mortality." (PMID 36457804, 2022). "Hypertension, an almost ubiquitous feature of CKD that contributes to both progression of CKD and CVD, may in part be related to Klotho deficiency." (PMID 32982966, 2020). "The patients with cerebral SVD progression had significantly old age (68.4 ± 8.8 years vs. 62.5 ± 12.8 years), higher prevalence of hypertension (72.4% vs. 53.3%) and lower level of plasma Klotho (251.8 ± 146.3 pg/mL vs. 354.3 ± 202.7 pg/mL) than those without cerebral SVD progression." (PMID 31398214, 2019). "Notably, in subjects younger than 57 years, neither in recessive model nor in dominant model was a significant association observed between the Klotho C1818T variant and the risk of CAD, hypertension, and CAD combined with hypertension." (PMID 30547758, 2018). "Since endothelial dysfunction is the one of the etiological factors of CAD and hypertension, it was hypothesized that the polymorphism of the human Klotho gene is involved in CAD and hypertension." (PMID 30547758, 2018). "Thus, as the need was strongly felt, this study evaluated the Klotho gene polymorphism in Iranian subjects to reveal its possible association with CAD, hypertension, and CAD combined with hypertension." (PMID 30547758, 2018). "Therefore, compound H attenuates arterial stiffening and hypertension through increasing circulating levels of Klotho." (PMID 29659128, 2018).
Hypertension (continued). "Moreover, to the best of the author’s knowledge, this is the first study reporting the association of Klotho gene polymorphisms with the risk of CAD, hypertension, and CAD combined with hypertension." (PMID 30547758, 2018). "This study demonstrated that Ang II stimulation and hypertension inhibited klotho expression." (PMID 27885332, 2016). "In the present study, THSG could reverse the inhibitory effect of Ang II and hypertension on klotho expression." (PMID 27885332, 2016). "A reduction in renal, serum, and urine levels of Klotho has been observed with normal ageing and in diseases characterised by premature vascular ageing such as renal disease as well as in animal models of disease such as diabetes and hypertension." (PMID 22121479, 2012). "Additionally, dietary Pi loading leads to suppression of Klotho, which may further contribute to hypertension." (PMID 41683565, 2026). "Elderly patients with hypertension show significantly lower serum klotho levels than those without hypertension, suggesting that the development of hypertension in the elderly population could be associated with reduced levels of klotho protein." (PMID 38696398, 2024). "Associations between ln(Klotho) and ePWV in postmenopausal women with and without hypertension." (PMID 39329104, 2024). "A cross-sectional study in postmenopausal women with hypertension found a significant inverse correlation between klotho concentration and hypertension, suggesting that serum klotho levels could be a useful biomarker for identifying women at risk of hypertension." (PMID 39616409, 2024). "This suggests that klotho may have a role in the pathogenesis of essential hypertension." (PMID 39616409, 2024). "Klotho levels were significantly reduced in essential hypertension cases compared to controls, Also, klotho had a negative direct association with essential hypertension indicating a potential role for klotho as a prognostic and predictive marker for essential hypertension." (PMID 39616409, 2024). "Similarly, Klotho gene delivery attenuates the progression of hypertension and kidney damage in spontaneous hypertensive rats, and ameliorates angiotensin II-induced kidney injury, improves endothelial function, and protects from uremic cardiomyopathy in heterozygous Klotho-deficient CKD mice." (PMID 36829798, 2023). "Moreover, in our study, the threshold value of serum Klotho concentration to predict all-cause mortality in patients with hypertension was 574 pg/mL, which has not been previously discussed." (PMID 36457804, 2022). "However, to the best of our knowledge, no previous study has evaluated the association between Klotho and mortality in individuals with hypertension." (PMID 36457804, 2022). "In addition, recombinant Klotho improved renal disease and hypertension in db/db mice." (PMID 35903083, 2022). "However, treatment with Klotho does prevent the progression of spontaneous hypertension." (PMID 22121479, 2012). "The interaction tests revealed significant modifications of the relationship between caffeine consumption and Klotho concentrations by variables including education, PIR, serum cotinine levels, sedentary activity, and hypertension (P for interaction <0.05)." (PMID 39723163, 2024). "A previous study reported that haplo-insufficiency of Klotho in mice results in increased aldosterone synthase (CYP11B2) expression, elevated plasma aldosterone, and high blood pressure." (PMID 38573585, 2024). "Conversely, Klotho downregulates RAAS activity, thus attenuating tissue injury and fibrosis and improving hypertension in experimental chronic kidney disease." (PMID 38573585, 2024). "Individuals with increased Klotho concentrations were younger, women, better educated, less likely to have CVD and hypertension, and less likely to be drinkers and smokers." (PMID 38027194, 2023).
Hypertension (continued). "For example, RhoA expression is increased in aging vessels, and klotho deficiency and high salt intake trigger noncanonical Wnt-Rho activation; klotho replacement therapy, Wnt inhibitors, and Rho-kinase inhibitors are expected to be new therapies in aging-associated hypertension." (PMID 33803946, 2021). "VDD+AmB/LE rats also presented alterations in the PTH-Klotho-FGF-23 signaling axis, urinary concentrating defect and hypertension, probably due to an inappropriate activation of the renin-angiotensin-aldosterone system." (PMID 31295336, 2019). "Nevertheless, larger studies with different ethnic populations are required to uncover the exact role of Klotho gene in the pathogenesis of CAD, hypertension, and CAD combined with hypertension." (PMID 30547758, 2018). "Gender, age, race, BMI, hypertension, and DM did not influence the negative relationship between serum S-Klotho and OA." (PMID 39556550, 2024). "After adjusting for confounding factors, ln(Klotho) was found to be significantly negatively correlated with arterial stiffness in postmenopausal women without hypertension." (PMID 39329104, 2024). "We performed interaction and subgroup analyses of ln(Klotho) and ePWV in postmenopausal women without hypertension." (PMID 39329104, 2024). "The SEM showed a significant negative correlation between klotho and blood pressure in essential hypertension cases." (PMID 39616409, 2024). "The results suggested that hypertension, BMI, Cr, Ca+2, PO-4, VLDL and Klotho were all related factors for cardiovascular complications, among which hypertension, BMI, Cr, Ca+2, PO-4 and VLDL and GAL-3 were risk factors (P<0.05), and the level of Klotho was a protective factor (P<0.05) (Table-V)." (PMID 37492290, 2023). "Risk factors related to cardiovascular complications were analyzed with cardiovascular complications as the dependent variable, age, hypertension, BMI, Cr, Ca+2, PO-4, GAL-3, Klotho, HDL, LDL and VLDL levels as independent variables, and 0.05 as the significance level of the selected variables." (PMID 37492290, 2023). "Additionally, an earlier animal study reported that Klotho protein was significantly suppressed in SHR, and introducing Klotho gene expression inhibited the progression of hypertension in SHR and alleviated renal damage." (PMID 37528365, 2023). "The serum klotho concentration did not significantly differ between patients with and without hypertension (P > 0.05) and between those with and without arterial stiffness (cfPWV ≥ 10 m/s) (P > 0.05)." (PMID 33504927, 2021). "Klotho expression in the heart in hypertension groups was not different from that in the corresponding sham groups." (PMID 34730891, 2021). "Participants with and without hypertension had similar serum klotho concentrations, body height, lipid profile, and pulse rate (P > 0.05)." (PMID 33504927, 2021). "Haplodeficiency of Klotho in mice leads to increased PWV and hypertension." (PMID 34820427, 2021). "In conclusion, our results confirm that vitamin D deficiency induces AmB/LE nephrotoxicity possibly due to impaired renal function accompanied by tubular injury, the arising of hypertension, alterations in the PTH-Klotho-FGF-23 signaling axis and water balance dysfunction." (PMID 31295336, 2019). "However, Klotho levels exhibited no significant impact on participants’ weight (BMI), serum albumin, cholesterol, serum phosphorus, blood calcium, history of hypertension, history of coronary heart disease, or history of smoking." (PMID 38287280, 2024). "Klotho levels in the heart and kidneys did not change significantly in either hypertension phase." (PMID 34730891, 2021). "Also, a significant negative correlation of klotho with essential hypertension was observed." (PMID 39616409, 2024).
Hypertension (continued). "Moreover, regression analysis also corroborated that the decrease in circulating Klotho levels observed in STEMI patients were independent of other cardiovascular comorbidities as the presence of DM, hyperlipidaemia, hypertension, or previous IHD." (PMID 39815421, 2025). "In the SHR and SHR-SP rats, the HFD did not reduce the Klotho expression further, suggesting that the regulation of Klotho is complex and may differ between HFD-induced and hypertension-induced conditions." (PMID 40869353, 2025).
hyperphosphatemia (108 papers, 2010 to 2026). Abnormally high level of phosphate in the blood. "Hyperphosphatemia and hypercalcemia are among the conditions associated with age-like syndrome found in Klotho-deficient mice, which indicate an imbalance in phosphate and calcium metabolism." (PMID 40119098, 2025). "On the other hand, hyperphosphatemia is caused by abnormalities in Klotho or FGF23; this seems to indicate that people with type 2 diabetes have a higher risk of developing CKD." (PMID 40119098, 2025). "DNA damage in vascular smooth muscle cells caused by hyperphosphatemia leads to cellular senescence, which further contributes to the premature aging process seen with klotho dysregulation or loss." (PMID 39113723, 2024). "The dysregulated Klotho pathway is significantly associated with hyperphosphatemia, endothelial dysfunction, vascular cell senescence, and renal epithelial cell death, contributing to the development and progression of CKD." (PMID 39544340, 2024). "Previous studies suggest that klotho function and dysregulation of the FGF23-klotho pathway, causing hyperphosphatemia and endothelial dysfunction, are associated with the pathogenic mechanisms of CKD development and disease progression." (PMID 39113723, 2024). "Hyperphosphatemia, as occurs in Klotho deficiency, appears to have a role in aging especially as related to CPP deposition in tissues." (PMID 39272986, 2024). "Genetic defects in klotho have been found to cause vascular calcification, hyperphosphatemia, nephropathy, growth retardation, multi-organ atrophy, and fibrosis." (PMID 37143722, 2023). "In Klotho-deficient mice, hypervitaminosis D and hyperphosphatemia both appear to contribute to the accelerated aging phenotype." (PMID 35903083, 2022). "Loss of renal klotho levels in patients with CKD-MBD is parallel to hyperphosphatemia, osteodystrophy, and vitamin D deficiency and is negatively associated with FGF23 levels." (PMID 35656113, 2022). "Klotho deficiency is associated with reduced renal function, hyperphosphatemia, increased FGF23 levels, renin–angiotensin–aldosterone system (RAAS) activation, inflammation, and chronic complications such as ectopic calcification, among others." (PMID 35887617, 2022). "Rare human mutations causing a severe deficiency of either Klotho or FGF23 are associated with hyperphosphatemia beginning at an early age." (PMID 35903083, 2022). "Mice deficient in Klotho or fibroblast growth factor 23 (FGF23) manifest a premature aging syndrome associated with hyperphosphatemia, which can be rescued by reducing blood phosphate levels with dietary interventions." (PMID 34439556, 2021). "Klotho-deficient mice are characterized by hyperphosphatemia and enormously increased levels of serum FGF-23." (PMID 34867481, 2021). "Clinically, the importance of the FGF23/klotho and S-klotho actions to attenuate the mortality risks associated with hyperphosphatemia were demonstrated in CKD patients stages 3–4." (PMID 34950686, 2021). "Some studies have demonstrated the harmful effect of Pi on insulin secretion in chronic renal patients associated with hyperphosphataemia and “Klotho”-deficient mice (kl/kl)." (PMID 34360534, 2021). "Then, CKD is considered to be a state of accelerated aging associated with hyperphosphatemia induced by Klotho deficiency." (PMID 33291777, 2020). "Stable delivery of adeno-associated virus (AAV) expressing sKlotho to Klotho deficient mice ameliorates hyperphosphatemia and relieves vascular calcification." (PMID 33362554, 2020). "Klotho-deficient mice develop premature aging, hyperphosphatemia, vascular calcification and endothelial dysfunction, and have shorter lifespans, while klotho overexpressing mice have 20–30% longer lifespans than wild type mice." (PMID 32545510, 2020).